FOXO3 (forkhead box O3)
Diseases named in the same sentence as FOXO3 in open-access papers (continued):
Sharing a sentence is not in itself a finding about the gene and the disease.
neurodegenerative disease (16 papers, 2009 to 2025). A disorder of the central nervous system characterized by gradual and progressive loss of neural tissue and neurologic function. "Forkhead box O3 (FOXO3), a transcription factor that plays a critical role in brain development and aging, is a longevity gene and is implicated as a causative gene of neurodegenerative diseases." (PMID 37408276, 2023). "Of note, the protective effect of CBX-mediated FOXO3 inhibition on neuronal cells might also be of great interest in regard to neurodegenerative diseases." (PMID 31591479, 2020).
metabolic disease (10 papers, 2012 to 2025). A congenital disorder (due to inherited enzyme abnormality) or acquired (due to failure of a metabolically important organ) disorder resulting from an abnormal metabolic process. "Importantly, interactions between SIRT1, peroxisome proliferator-activated receptor gamma coactivator 1 (PPARGC1A), and FOXO1/FOXO3 indicate a strong mitochondrial and antioxidant component, aligning with their roles in metabolic disease and aging." (PMID 40664894, 2025). "Therefore, Foxo3 may be partly involved in PCB-induced metabolic diseases." (PMID 26086818, 2015). "Notably, the human data demonstrate that exercise mode dictates the magnitude and persistence of FoxO3-autophagy coupling, and metabolic disease can selectively mute FoxO3 nuclear function without abolishing autophagy, implying compensatory activation of parallel axes such as ULK1/AMPK." (PMID 40861274, 2025).
kidney diseases (8 papers, 2017 to 2025). "The stress-responsive transcription factor forkhead box O3 (FoxO3) activates autophagy in chronic hypoxia through the transactivation of autophagy proteins and plays a protective role in kidney diseases." (PMID 31936109, 2020).
neurological diseases (5 papers, 2020 to 2025). "Herein, it would be important to further investigate how FOXO3 regulates autophagy in different cell types of brain to offer various targets for different nervous system diseases." (PMID 34354990, 2021).
adenocarcinoma (4 papers, 2013 to 2023). A common cancer characterized by the presence of malignant glandular cells. "Therefore, the level of nuclear FOXO3 is decreased, which prevents FOXO3 from playing an anticancer role and mediates the promotion of adenocarcinoma growth by IGF-1." (PMID 36831629, 2023).
hematological malignancies (4 papers, 2017 to 2022). "Thus, our findings indicate that aberrant expression of miR-9 blocks erythropoiesis by deregulating FoxO3-mediated pathways, which may contribute to the ineffective erythropoiesis observed in patients with hematological malignancies." (PMID 29695725, 2018).
infectious disease (4 papers, 2014 to 2023). A disorder directly resulting from the presence and activity of a microbial, viral, or parasitic agent in humans. "Recent studies have suggested that FOXO3 plays vital roles in the risk of immune–related infectious diseases such as TB." (PMID 31241240, 2019). "Here, we highlight the previously under-appreciated role that genetics has in determining prognosis in autoimmune and infectious disease, and the common role that FOXO3 has been shown to have as a modulator of inflammatory responses, and thereby of outcome, across several distinct diseases." (PMID 25505963, 2014).
inflammation (4 papers, 2010 to 2022). Aberrant reaction of the microcirculation characterized by movement of fluid and leukocytes from the blood into extravascular tissues. "Noteworthy, FOXO3 transcription factor was found to associate with chronic periapical inflammation in periapical lesion specimens via IL-1β release regulation." (PMID 35955417, 2022).
myopathy (4 papers, 2013 to 2024). A disease of the muscle in which the muscle fibers do not function properly. "FOXO3 is understood to be generally anti-inflammatory as its deficiency leads to spontaneous lymphoproliferation, T Cell hyperactivation, inflammatory myopathies, and idiopathic autoimmune disorders." (PMID 38333571, 2024). "At the mRNA level, the essential insulin-dependent metabolic gene AKT2 and the down-regulated genes, namely FOXO3, were significantly upregulated in muscle parts with critical myopathy and without critical myopathy, compared to controls." (PMID 36904071, 2023).
respiratory diseases (4 papers, 2017 to 2024). "Forkhead box O3 (FOXO3) is a gene involved in the etiology of a number of respiratory diseases." (PMID 29141605, 2017).
bacterial infection (3 papers, 2016 to 2023). "The differentially expressed genes NF-κB1, FOXO3 and PAX5 are involved in defending the host against bacterial infections were significantly enriched in the indigenous breed Kashmir favorella." (PMID 37098463, 2023).
FOXO3 also shares sentences with these, for which no sentence is quoted: idiopathic pulmonary fibrosis (13 papers); oral squamous cell carcinoma (9); Crohn disease (8); vitiligo (8); heart disease (7); invasive ductal breast carcinoma (6); thymic lymphomas (6); acute promyelocytic leukemia (5); alveolar rhabdomyosarcoma (5); colorectal (5); HCMV infection (5); amyotrophic lateral sclerosis (4); essential hypertension (4); hypertriglyceridemia (4); kidney damage (4); motor neuron disease (4); squamous cell carcinoma (4); thyroid (4); ulcerative colitis (4); acute monocytic leukemia (3); astrocytoma (3); breast invasive carcinoma (3); chronic lymphocytic leukemia (3); cognitive disorder (3); Disc Degeneration (3); Hodgkins lymphoma (3); kidney injury (3); memory impairment (3); Parkinson (3); urothelial carcinoma (3).
A further 154 diseases each share a sentence with FOXO3 in 3 papers or fewer.